YTHDF2 (YTH N6-methyladenosine RNA binding protein F2)
Diseases named in the same sentence as YTHDF2 in open-access papers (continued):
Sharing a sentence is not in itself a finding about the gene and the disease.
tumor (continued). "However, it should be noted that the effects of YTHDF2 in that study contradict earlier reports, which we suspected could be due to tumor heterogeneity in HCC." (PMID 32733807, 2020). "Importantly, restoring YTHDF2 expression defined m6A decoration as a tumor suppressive mechanism." (PMID 31735169, 2019). "Overall, these findings highlight the importance of Mettl3-mediated m6A modification at the 3’UTR of Smad3 mRNA in its low expression in tumor MO-MDSC, due to impaired mRNA stability by Ythdf2 recognition." (PMID 41360769, 2025). "For example, in colorectal cancer, METTL14 inhibits the proliferation, metastasis and invasion of tumor cells either by enhancing the expression of KLF4 in IGF2BP2-m6A manner, or by inhibiting YTHDF2-mediated SOX472, or by suppressing XIST." (PMID 40734692, 2025). "Clinical analyses further reveal a positive correlation between VEGFA expression and RBM15/IGF2BP3/YTHDF2 levels, underscoring the central role of RBM15-mediated m6A modification in VEGFA regulation and tumor angiogenesis." (PMID 41403702, 2025). "Strikingly, Mettl3-mediated m6A modification destabilized Smad3 mRNA via Ythdf2-dependent recognition of a specific m6A site (position 4591) in the 3’UTR, accounting for impaired tumor MDSC maturation." (PMID 41360769, 2025). "In melanoma cells, knocking down the FTO gene can accelerate the RNA degradation rate of intrinsic pro-tumor genes including PD-1, CXCR4 and SOX10 through YTHDF2." (PMID 40675967, 2025). "In NSCLC, VIRMA mediated the m6A modification of DAPK3, facilitating YTHDF2/3-mediated DAPK3 post-transcriptional degradation and promoting tumor growth." (PMID 40723784, 2025). "YTHDF2 also influences ceramide metabolism and related pathways (e.g., extracellular signal‐regulated kinase [ERK] and PI3K/AKT), further driving tumor progression." (PMID 39802639, 2025). "Notably, YTHDF1 and YTHDF2 promote the recruitment of tumor-infiltrating lymphocytes (TILs), enhancing immune surveillance while simultaneously suppressing PD-L1 expression to facilitate immune cell-mediated tumor destruction, thus establishing an inflammatory tumor milieu." (PMID 40740874, 2025). "Myeloid-specific Ythdf2 deletion blocks MDSC differentiation and infiltration, enhances anti-tumor immunity, and reverses radioresistance." (PMID 41403953, 2025). "Sh‐YTHDF2 and DNase I inhibited GPX4, SLC7A11, and FTH1 expression in the tumour, while increasing ACSL4 and PTGS2 levels and had a superimposed effect." (PMID 39865544, 2025). "circMET functions as a molecular scaffold that physically interacts with YTHDF2, facilitating its recruitment to CDKN2A mRNA and thereby promoting m6A-dependent decay of this tumor suppressor transcript." (PMID 40986143, 2025). "Skin-specific deletion of Ythdf2 in mice enhanced the UVB-induced skin inflammatory response and promoted tumor initiation." (PMID 41224760, 2025). "METTL3/14, YTHDF2/YTHDC1 proteins work to maintain the activity of oncogenes, inhibit tumor suppressor genes, and drive cancer development by regulating m6A RNA modification." (PMID 41446042, 2025).
tumor (continued). "NK, as an immune cell responsible for recognizing and killing tumor cells, can also be regulated by LncRNAs through a variety of mechanisms.For example, LINC00707 can interact with YTHDF2, promoting ubiquitination dependent degradation of YTHDF2 protein." (PMID 40352941, 2025). "In xenograft models, silencing RBM15, IGF2BP3, or YTHDF2 significantly reduces VEGFA expression and suppresses tumor growth." (PMID 41403702, 2025). "YTHDF2 binds to m6A U6 to compete with TLR3 binding to m6A U6, thus inhibiting the expression of inflammatory modulators, cell proliferation, and tumor growth." (PMID 41224760, 2025). "Analyses of MeRIP-seq, mRNA-seq, and databases have identified LHPP and NKX3–1 as the main targets of YTHDF2, and both LHPP and NKX3–1 are tumor suppressors that regulate tumor progression by inhibiting AKT phosphorylation." (PMID 38166703, 2024). "Another study indicated that YTHDF2 stabilises MYC and VEGFA in GBM stem cells through m6A‐dependent mechanisms, promoting CSC‐like phenotypes in tumour cells." (PMID 39135292, 2024). "While YTHDF2 knockdown has been shown to inhibit HCC cell proliferation, other studies have highlighted its tumor-suppressive role by targeting genes such as EGFR, IL11, and SRPINE2." (PMID 38395751, 2024). "YTHDF2 degrades IL11 and SERPINE2 mRNA, and inhibits tumor growth, vascular density and permeability, and inflammation in hepatocellular carcinoma." (PMID 39457524, 2024). "YTHDF2 negatively regulates circPOLR2A, resulting in ERK pathway inactivation and ultimately suppressing angiogenesis, metastasis, and tumor growth." (PMID 39098905, 2024). "Inhibition of tumor cell proliferation can be achieved by blocking METTL3, TRMT6/TRMT61A, the IGF2BP family, YTHDF2, or ALKBH5." (PMID 39372415, 2024). "Taken together, YTHDF2 is likely the downstream executed reader following METTL3 targeting, thus playing a pivotal role in the anti‐tumour response." (PMID 39568154, 2024). "In pancreatic cancer, YTHDF2 modulates EMT and proliferation differentiation through the HIPPO/YAP axis, aiding tumour immune evasion." (PMID 39135292, 2024). "The IHC and western blot results showed that both GL‐1 and GC‐7, as DHPS inhibitors, inhibited METTL3, YTHDF2, and YTHDC1 in tumor tissues." (PMID 38952061, 2024). "By inhibition of miRNA-495, its downstream target, YTHDF2, is overexpressed which induces MOB3B degradation by recognizing m6A sites on its mRNA, thereby promoting tumor progression." (PMID 38075202, 2024). "In CRC, glutamine enhances m6A methylation and YTHDF2‐mediated degradation of ATF4 mRNA, stimulating autophagy and impairing anti‐tumour efficacy." (PMID 39135292, 2024). "To explore how YTHDF2 modulate the interaction between HCC cells and tumor microenvironment, we analysis the single cell RNA‐sequencing data of GSE202642." (PMID 38247171, 2024). "The m6A modification plays an indispensable role in maintaining the tumor infiltration and cytotoxicity of NK cells, primarily regulated by METTL3, METTL14, and YTHDF2." (PMID 39372415, 2024). "Research has shown that m6A readers such as IGF2BP2, IGF2BP3, YTHDF2, and YTHDF3 are involved in tumor angiogenesis, further influencing the occurrence and development of tumors and potentially affecting the prognosis of patients with tumors to some extent." (PMID 39295872, 2024). "For instance, YTHDF2 targets various factors such as STAT5 and Eemesodermin to maintain NK cell homeostasis, maturation, and anti-tumor immunity." (PMID 38075202, 2024). "Immunohistochemical images showed the expression levels of RBM15, VIRMA, YTHDC2, YTHDF2, METTL14, and IGF2BP2 proteins in tumor tissues." (PMID 36791151, 2023). "We further confirmed the BAMBI reduction in tumor-infiltrating MDSCs from WT+IR versus WT mice and the BAMBI induction in MDSCs from Ythdf2-cKO versus WT mice at both mRNA and protein levels." (PMID 38099498, 2023).
tumor (continued). "As a tumor suppressor in CC, the m6A site of GAS5 mRNA was recognized and silenced by YTHDF2, which promoted the proliferation, migration, and invasion of tumor cells." (PMID 37951987, 2023). "YTHDF2 significantly downregulated total mRNA m6A levels to enhance EOC cell proliferation and migration, and its overexpression rescued the tumour suppressive effect induced by the target gene miR-145." (PMID 37194218, 2023). "However, overexpression of MCM2/5 could not entirely restore tumor growth arrest caused by YTHDF2 depletion, which warrants further studies to identify additional targets of YTHDF2 that participate in HBV-related HCC progression." (PMID 36765030, 2023). "In lung squamous cell carcinoma, up-regulation of YTHDF2 under hypoxic conditions activates the mTOR/AKT signaling pathway and induces EMT to play a tumor-promoting role." (PMID 36999016, 2023). "Glutaminolysis blockade enhanced FTO expression and disrupted YTHDF2-mediated RNA decay of activating transcription factor 4 (ATF4), stimulating autophagy activation and compromising anti-tumour efficacy." (PMID 36859310, 2023). "Depletion of tumor-intrinsic ALKBH5 enhanced m6A modification on PD-L1 mRNA, and promoted its degradation in a YTHDF2-dependent manner." (PMID 36810108, 2023). "By stimulating the proteasome degradation of YTHDF2 in OC, FBW7 mitigates YTHDF2’s tumor-promoting impact." (PMID 36831377, 2023). "It has been shown that by inhibiting YTHDF2-mediated BMF mRNA downregulation, FBW7 inhibits tumor growth and metastasis in OC." (PMID 36831377, 2023). "Cancer cells cannot proliferate, migrate, or invade in vitro or in vivo if their lncRNA, THOR, is lost, while the m6A readers YTHDF1 and YTHDF2 can regulate THOR, thus inhibiting tumour formation in vivo and in vitro." (PMID 37542290, 2023). "YTHDC1, HNRNPC, HNRNPA2B1, YTHDF1, YTHDF2, and YTHDF3 all showed significantly high expression in ccRCC (all p-values < 0.0001) compared to the average overall gene expression in the tumour tissue." (PMID 36899967, 2023). "Except METTL14, YTHDF2 and YTHDF3, all m6A related genes expression were significantly different between tumor and control group." (PMID 37194014, 2023). "Among the regulatory genes, ALKBH1 and ALKBH3, which are methylation erasers, were upregulated and TRMT10C, TRMT6, TRMT61B, YTHDF2, and YTHDF3 were downregulated in tumor samples in comparison to normal tissues." (PMID 37679761, 2023). "Some m6A regulators are abnormally expressed in OC, such as YTHDF1, YTHDF2, METTL3, ALKBH5 etc., and promote or disrupt the development or maintenance of tumour phenotypes." (PMID 35303965, 2022). "Clinically, YTHDF2 expression exhibited a positive correlation with ZEB1 expression in both TCGA database and BC tumor tissues (n = 82) from our independent cohort." (PMID 36302751, 2022). "In ICC, tumor-intrinsic ALKBH5 removes m6A modification in PDL1 mRNA’s 3′UTR and reduces its degradation in a YTHDF2-dependent manner, thus inhibiting cytotoxicity of T cells and mediating immune escape of ICC cells." (PMID 35063010, 2022). "Overexpression of YTHDF2 accelerated the degradation of phosphate and tension homology deleted on chromosome ten (PTEN) mRNA, a remarkable tumor suppressor, which considerably increased the proliferation, invasion, and migration of GC cells." (PMID 35382893, 2022). "The m6A reader protein YTHDF2-dependent RNA degradation pathway mediates the degradation of SOCS2 mRNAs, suggesting that METTL3 represses the expression and stability of critical tumor suppressor genes at the posttranscriptional level." (PMID 36446846, 2022). "This is due to knockout of YTHDF2 can reduce the m6A level of OCT4 5’-UTR, and the expression of OCT4 protein, thereby affecting the stemness of tumor cells." (PMID 35022030, 2022).
tumor (continued). "There is also an interaction between Ms, with knockdown of FTO increasing m6A methylation in key pro-tumor cell-intrinsic genes including PD-1, SOX10 and CXCR4, resulting in increased RNA decay through the reader YTHDF2." (PMID 35265626, 2022). "Our results suggested a correlation between YTHDF2 and TME composition, as well as its vital role in immune infiltration and immunotherapeutic response in a majority of tumor types." (PMID 36120577, 2022). "YTHDF2 affected the migration and invasion of tumour cells by regulating the EMT, but the pathological pathway by which YTHDF2 induces the EMT remained unclear." (PMID 35186724, 2022). "Yellow background indicated the most significant (p < 0.0001) genes up-regulated in tumor tissues, including HNRNPC, YTHDF1, IGF2BP1, YTHDF2, RBM15, and IGF2BP3." (PMID 35581263, 2022). "In terms of the relationship between YTHDF2 and tumor vessels, a study suggested that serine-type endopeptidase inhibitor 2 (SERPINE2) was upregulated in YTHDF2-silenced cells, thereby promoting angiogenesis and growth of HCC." (PMID 35937999, 2022). "We found that with the exception of RBM15/15B, YTHDF2, ZC3H13, all other regulators were significantly correlated with tumor occurrence (P < 0.05)." (PMID 35572524, 2022). "We found that YTHDF2 is expressed at high levels in CRC, and its expression is positively correlated with tumour growth." (PMID 34709763, 2021). "Compared with xenografts derived from cells expressing the empty vector, the YTHDF2- and METTL3-overexpressing xenografts showed accelerated tumor progression." (PMID 34246306, 2021). "Our data show that seven m6A regulators (CBLL1, ELAVL1, LRPPRC, RBM15B, YTHDF1, YTHDF2, and ZC3H13) are related to tumorigenesis, tumor microenvironment and tumor prognosis." (PMID 33670062, 2021). "MiR-145 can regulate the m6A levels by targeting the 3’-UTR of YTHDF2 mRNA in HCC cells, thereby exerting a tumour suppressor effect." (PMID 34246319, 2021). "We found that METTL3, RBM15B, YTHDC2, YTHDF2, and HNRNPA2B1 were indeed highly expressed in the tumor samples." (PMID 34336856, 2021). "METTL3, VIRMA, and hnRNPC showed higher expression in tumor samples, while METTL14, ZC3H13, FTO, ALKBH5, YTHDF2, YTHDC1, and YTHDC2 showed higher expression in normal tissue samples 53,152,156,157." (PMID 33390849, 2021). "The expression of YTHDF2 in HCC is specifically induced by hypoxia, and overexpression of YTHDF2 inhibits cell proliferation, tumor growth and the activation of MEK and ERK." (PMID 33708621, 2021). "Zhong and colleagues found that YTHDF2 represses cell proliferation and growth in HCC and functions as a HCC tumor suppressor via destabilizing EGFR transcript." (PMID 34272618, 2021). "The AUC of the m6A risk model in 1/2/3 years was better than that of the expression of other genes (KIAA1429, YTHDF2, and RBM15B) and other factors, such as age, sex, and tumour grade." (PMID 34512165, 2021). "By comparing 50 normal and 374 tumor tissues, METTL14, YTHDC1, ZC3H13, ALKBH5, YTHDF2, and RBM15 had extremely lower expression in tumor tissues (p < 0.001)." (PMID 34277622, 2021). "In recent years, increasing studies have confirmed that m6A methylation‐related genes, such as ALKBH5, FHL2, DGCR8, YTHDF2, YTHDF3, and PICM8, were overexpressed in tumor tissues and closely related to malignant tumors." (PMID 33264518, 2021). "Simultaneously, YTHDF2 exerts an inhibitory effect on HCC, inhibiting growth of tumor cells and vessels by processing interleukin 11 (IL11) mRNA and serpin family E member 2 (SERPINE2) mRNA." (PMID 34105069, 2021). "Over-expression of YTHDF2 inhibited proliferation and cell cycle progress in ESCC cells, indicating its tumor suppressive role in ESCC." (PMID 34544449, 2021). "Regarding tumor stemness, in this study, YTHDF2, HNRNPA2B1, HNRNPC, IGF2BP1, and KIAA1429 were positively correlated with tumor stemness, while FTO was negatively correlated with tumor stemness." (PMID 35003079, 2021).
tumor (continued). "Mechanistically, YTHDF2 degrades m6A-modified IL-11 and SERPINE2 mRNA, resulting in inflammation-mediated malignant tumours and vascular normalization." (PMID 34246319, 2021). "In accordance with our results, METTL3, YTHDF2, and YTHDF1 were found to be considerably overexpressed between tumor and normal adjacent tissues." (PMID 34248650, 2021). "The results showed that ELAVL1, YTHDF2, RBM15, HNRNPA2B1, ALKBH5A, and RBM15B expression was significantly upregulated in tumor tissues compared with normal tissues (p < 0.05)." (PMID 34900988, 2021). "YTH domain proteins, including YTHDF1, YTHDF2, YTHDF3, YTDHDC1 and YTHDC2, are the most reported m6A readers and promote the degradation of m6A modified mRNA and tumor progression." (PMID 34295828, 2021). "The tumor cells exhibited a significant increase in the expression of WTAP, YTHDF2, and YTHDF3, but a reduction in the expression of FTO and ALKBH5 compared to the normal epithelial cells in the para-tumor samples." (PMID 34733841, 2021). "In contrast, overexpression of YTHDF2 in LN229 cells enhanced the tumor growth and invasiveness and reduced the survival of tumor-bearing mice." (PMID 33420027, 2021). "Specifically, HNRNPC, YTHDF1, YTHDF2, METTL3, RBM15, YTHDF3, and KIAA1429 are highly expressed in tumor tissues." (PMID 32258108, 2020). "YTHDF2 expression also impacted the OS in LGG, LIHC, and SARC with different clinicopathological parameters, such as gender and tumor grade." (PMID 32986017, 2020). "YTHDF2 promotes CSC liver phenotype and tumor metastasis by regulating the 5′-UTR m6A level of OCT4 mRNA." (PMID 33552994, 2020). "Five m6A-related genes (ZC3H13, METTL14, YTHDF2, YTHDF3 and HNRNPA2B1) showed significantly downregulated in tumor tissue, while seven regulators (YTHDC2, FTO, WTAP, METTL3, ALKBH5, RBM15 and KIAA1429) was remarkably upregulated in ccRCC." (PMID 32419773, 2020). "A study reported by Zhong and colleagues showed that HIF1α-dependent hypoxia downregulated the expression of YTHDF2 in HCC cells, and that YTHDF2 depletion promoted tumor cells proliferation." (PMID 32276589, 2020). "With TCGA cohort, we examined the four common m6A readers (YTHDF1, YTHDF2, YTHDF3, and YTHDC1) in LUAD tumor samples and normal samples, and found YTHDF1 highly expressed in tumor tissues." (PMID 32195181, 2020). "We carried out xenograft tumor experiments on the nude mice in order to verify the effect of KDM5A on PCa initiation and progression via the miR-495/YTHDF2/MOB3B axis in vivo." (PMID 33087165, 2020). "In this study, we demonstrated the tumour‐promoting function and specific regulatory mechanism of m6A axis, consisting of the core ‘writer’ protein METTL3 and the major reader protein YTHDF2." (PMID 32126149, 2020). "Further, YTHDF2 facilitates YAP mRNA decay via the AGO2 system in normal tissue, while YTHDF1 promoted YAP mRNA translation by interacting with eIF3a in tumor tissue." (PMID 32106857, 2020). "Comparisons between adjacent normal and tumor samples identified seven down-regulated (METTL14, WTAP, YTHDC1, YTHDC2, ALKBH5, FTO, and YTHDF2) and one up-regulated (YTHDF1) regulators." (PMID 32500031, 2020). "Our analysis in both protein (MS) and mRNA (TCGA) datasets suggested that writers and readers were tumor suppressive while erasers play a tumorigenic role in GC, however, controversial roles of METTL3/YTHDF2 in other cancer types were reported." (PMID 31243897, 2019). "In line with this, YTHDF2 silencing in MHCC97H tumors led to increased dextran leakage and PAS+CD31− fluid-filled channels lined by tumor cells, indicating intensified vascular permeability and mimicry." (PMID 31735169, 2019). "The reduction of YTHDF2, which predicts poor classification and prognosis of HCC patients, highly correlates with this epitranscriptional orchestration and promotes tumor growth and metastasis." (PMID 31735169, 2019).